RNU7-138P (RNA, U7 small nuclear 138 pseudogene)
Gene: Small nuclear RNA gene on chromosome 2 (10,744,186 to 10,744,249, forward strand). Ensembl gene ENSG00000239053.
Homologues: Orthologues: chimpanzee U7 (95% identical), macaque U7 (95% identical). Paralogues in human: RNU7-167P (81% identical), RNU7-140P (80% identical), RNU7-172P (80% identical), RNU7-70P (80% identical), RNU7-88P (80% identical), RNU7-111P (78% identical), RNU7-34P (78% identical), RNU7-10P (77% identical), RNU7-187P (77% identical), RNU7-40P (77% identical), RNU7-48P (77% identical), RNU7-50P (77% identical), and 142 more.